COMP (cartilage oligomeric matrix protein)
Diseases named in the same sentence as COMP in open-access papers (continued):
Sharing a sentence is not in itself a finding about the gene and the disease.
breast carcinoma (continued). "Cartilage oligomeric matrix protein (COMP) is an emerging independent prognostic marker for breast cancer patients." (PMID 34884987, 2021). "This study aimed to assess COMP as a potential biomarker in the group of metastatic breast cancer patients." (PMID 34884987, 2021). "Taken together, COMP emerges as a biomarker of advanced breast cancer progression, especially in ER-positive and HER2-positive patients." (PMID 34884987, 2021). "COMP affects the migration, invasion, and metabolism of the breast cancer cells as well as the abundance of cancer stem cells." (PMID 34884987, 2021). "High COMP expression in lymph node metastases in breast cancer has prognostic implications suggesting that COMP is involved in the progression to a more aggressive metastatic disease." (PMID 34884987, 2021). "The goal of the current study was to further evaluate COMP as a potential biomarker in metastatic breast cancer patients by assessing the serum COMP levels and COMP expression in relation to the severity of the disease and outcome." (PMID 34884987, 2021). "It is clear that breast cancer cells can express COMP since we detected it in an intracellular location when using IHC." (PMID 34884987, 2021). "We also found increased levels of COMP in sera of metastatic breast cancer (MBC) patients compared with those with early breast cancer." (PMID 34884987, 2021). "Whole COMP has been recognized as a novel biomarker for colon and breast cancer, little data exist regarding its clinical significance and biological functions in PTC." (PMID 33613749, 2021). "The potential role of COMP in tumors has been reported in breast cancer, prostatic cancer and colon cancer, and a high expression level of COMP has been detected both in tumor cells and the surrounding stroma." (PMID 30999932, 2019). "One molecular mechanism by which COMP leads to the poor survival of breast cancer patients has recently been revealed." (PMID 31737569, 2019). "In breast cancer, COMP expression has been evaluated in tumor tissue samples by immunostaining, but to date no study has evaluated the prognostic value of COMP serum levels." (PMID 31737569, 2019). "A strong COMP expression in tumor cells was recently correlated with reduced breast cancer-specific survival and recurrence-free survival of breast cancer patients as an independent prognostic marker." (PMID 31737569, 2019). "One of the tested compounds that COMP expressing cells exhibited resistance against was Docetaxel, which is broadly used as first line chemotherapy drug in breast cancer." (PMID 31737569, 2019). "In contrast, a positive ELISA COMP serum sample (≥12 U/L) was able to predict worse survival for a breast cancer patient in the same population of patients." (PMID 31737569, 2019). "Emerging evidence shows that COMP plays critical roles in tumor development, including breast cancer, colon cancer and hepatocellular carcinoma (HCC)." (PMID 30231922, 2018). "Recent studies have shown that COMP promotes the progression of breast cancer, colon cancer and prostate cancer." (PMID 30231922, 2018). "This clinical observation was confirmed in a mouse xenograft model and we, additionally, identified mechanisms responsible for the new function of COMP in breast cancer." (PMID 29228690, 2017). "In the current study, we observed a similar effect of COMP expression in prostate cancer, although it is worth noting that a larger percentage of breast cancer specimens express COMP (79%) as compared to prostate cancer (17%)." (PMID 29228690, 2017). "Previously, we showed that COMP expression protects breast cancer cells against ER stress-mediated apoptosis." (PMID 29228690, 2017). "We have previously shown that COMP protects breast cancer cells against ER stress-mediated apoptosis." (PMID 29228690, 2017). "Firstly, COMP expression protects breast cancer cells from endoplasmic reticulum (ER) stress and, secondly, cells expressing COMP undergo a metabolic switch i.e. a Warburg effect." (PMID 29228690, 2017).
breast carcinoma (continued). "In a previous study, we showed that secreted COMP binds back to the surface of transfected breast cancer cells." (PMID 29228690, 2017). "Our previous study showed that breast cancer cells expressing COMP were characterized by significantly decreased oxidative phosphorylation (OXPHOS)." (PMID 29228690, 2017). "Our previous study showed that COMP expression in breast cancer correlates with poor patient survival, formation of larger tumors in vivo, increased invasion in vitro, protection against ER stress-mediated apoptosis, as well as an enhanced Warburg effect." (PMID 29228690, 2017). "This study suggests the COMP-PMEPA1 axis as a new driver of EMT in breast cancer models." (PMID 41689303, 2026). "Here, we investigated the role of COMP in regulating EMT in breast cancer." (PMID 41689303, 2026). "We hypothesized that COMP may mediate chemoresistance in breast cancer based on several previous findings." (PMID 38965233, 2024). "This association was also observed for COMP expression in the tumor stroma in intestinal-type periampullary adenocarcinoma, but not in breast cancer patients." (PMID 38615020, 2024). "However, breast cancer patients treated in the clinic with various therapies and expressing high levels of COMP in tumors had worse overall survival." (PMID 38965233, 2024). "Unexpectedly, we detected COMP expression in tumors from patients with breast cancer." (PMID 37207219, 2023). "Multiple lines of evidence strongly indicate the role of COMP in breast cancer metastasis." (PMID 36012514, 2022). "The enhanced expression level of COMP in tumor cells is significantly related to the reduced breast cancer-specific survival rate and recurrence-free survival rate of patients, while the expression level of COMP in the stroma has a poor connection with prognosis." (PMID 35433683, 2022). "Studies have shown that COMP contributes to the development and metastasis of breast cancer." (PMID 35433683, 2022). "In addition, the expression of COMP in breast cancer cells, mediates the interaction between Jagged1 and Notch3, leading to the alteration of the cancer stem cells in vitro and in vivo." (PMID 36114508, 2022). "COMP is also found to be highly expressed in tumor tissues, such as hepatocellular carcinoma, colon cancer, and breast cancer, and is often related to a high recurrence rate and low survival rate in cancer patients, serving as an independent prognostic biomarker." (PMID 36012514, 2022). "We recently revealed that COMP levels in the serum of breast cancer patients could serve as an independent prognostic marker." (PMID 34884987, 2021). "Furthermore, high S-COMP levels correlated with the presence of bone metastases, indicating a possible role of COMP in bone metastatic progression of breast cancer." (PMID 34884987, 2021). "The serum level of COMP appears to be a valuable marker of breast cancer progression as it could distinguish ER or HER2 positive patients with advanced disease." (PMID 34884987, 2021). "One weakness of the current study lies in the limited number of patients that were included, and, therefore, further studies including larger cohorts will be needed to fine-tune conclusions on how to best use COMP as biomarker in the management of breast cancer." (PMID 34884987, 2021). "Recently, COMP expression was also documented in breast cancer patients both in sera and tumor biopsies, in both of which it could serve as an independent prognostic marker." (PMID 34884987, 2021). "In previous studies, COMP expression by the tumor cells but not in stroma was associated with a worse prognosis of patients with early breast cancer." (PMID 34884987, 2021). "Moreover, it has been proven that COMP can protect breast cancer cells from endoplasmic reticulum stress-induced apoptosis." (PMID 33613749, 2021). "Interestingly, COMP protein expression was studied by immunohistochemistry in two cohorts of breast cancer patients (n = 122 and n = 498)." (PMID 33540589, 2021).
breast carcinoma (continued). "Despite this loss, COMP expression in cancer and stromal cells in LNM was associated with progression-free and overall survival from the date of metastasis as well as from the primary breast cancer diagnosis." (PMID 34884987, 2021). "COMP has been shown in recent studies to be a promising new marker for breast cancer." (PMID 33227073, 2020). "COMP was reported to promote fibrosis in multiple organs, such as the skin, lung, and liver, and also contributes to the development of tumors, including colon cancer, breast cancer, and hepatocellular carcinoma." (PMID 33042984, 2020). "The mechanisms behind the observation that COMP expression in cancer is detrimental may rest in the fact that COMP expressing breast cancer tumors have a larger proportion of cancer stem cells." (PMID 31737569, 2019). "F5 also demonstrated strong similarity to published myCAF signatures, including Elyada myCAF and LRRC15+ fibroblasts from pancreatic cancer, pan-cancer C10_COMP+ CAF, ECM/TGFβ myCAF from breast cancer and Liu myCAF from PCa." (PMID 41378308, 2025). "COMP, an ECM protein, was reported as a prognostic factor in colorectal cancer, favored the development and metastasis of breast cancer, and drove hepatocellular carcinoma progression." (PMID 38918720, 2024). "Exosome-derived COMP partially contributes to EMT in recipient cells by increasing MMP9, MMP3, BMP1, TGFB2, ZEB1, and SNAI2 (ER+ human breast cancer cell line, MCF7 cells)." (PMID 36012514, 2022). "We found that COMP promoted the migration and invasion of PTC cells, which is similar to its function in breast cancer cells 19; we also found that COMP was related to PTC metastasis." (PMID 33613749, 2021). "In a small initial patient cohort analyzed in this study, the expression of COMP by immunohistochemical staining failed to predict breast cancer patients' survival." (PMID 31737569, 2019). "Here, we show that COMP expression is not breast cancer-specific, but also plays an important role in the progression of prostate cancer and we identify additional molecular mechanisms underlying this function." (PMID 29228690, 2017). "Immunostaining of 342 prostate cancer specimens in tissue microarrays showed that COMP expression is not breast cancer-specific but also occurs in prostate cancer." (PMID 29228690, 2017). "The COMP-induced chemoresistance was independent of the breast cancer subtype." (PMID 38965233, 2024). "Herein, we show that cartilage oligomeric matrix protein (COMP) expression leads to increased cancer cell survival and attenuated apoptosis under treatment with several chemotherapeutic drugs, anti-HER2 targeted treatment, and endocrine therapy in several breast cancer cell lines tested." (PMID 38965233, 2024). "Thus, COMP levels in sera can be measured using a commercial, IVD approved ELISA method, which yields results that can be immediately applied in oncological clinics for breast cancer patient stratification and therapeutic tailoring." (PMID 31737569, 2019). "Comparisons of serum COMP levels to primary tumors and lymph node metastases (LNM) COMP IHC expression were not performed since the serum samples were obtained at diagnosis of metastatic disease and not at the initial breast cancer diagnosis." (PMID 34884987, 2021).
colon carcinoma (31 papers, 2016 to 2025). "Similar associations of COMP expression being related to survival and time to recurrence have been found in studies on patients with colon cancer, hepatocellular carcinoma, and urothelial carcinoma." (PMID 38563861, 2024). "Studies in colon cancer and pancreatobiliary adenocarcinoma have revealed COMP expression to be associated with decreased infiltration of immune cells in the tumor microenvironment." (PMID 38563861, 2024). "High COMP levels have also been associated to breast cancer, hepatocellular carcinoma, prostate cancer, and colon cancer." (PMID 37838792, 2023). "COMP overexpression in colon cancer cell lines was linked with the promotion of cell proliferation by altering the PI3K-Akt-mTOR axis." (PMID 37207219, 2023). "Herein, we selected COMP, which was the intersection of the output results from the two training cohorts, as the key gene associated with CAFs in colon cancer patients." (PMID 36671447, 2022). "In recent studies, COMP has also been associated with worse outcome when it is expressed in prostate cancer, in colon cancer as well as in hepatocellular carcinoma." (PMID 31737569, 2019). "COMP is significantly upregulated and associated with poor survival in colon cancer." (PMID 41009743, 2025). "However, in the context of other types of cancer, such as colon cancer and a certain type of pancreatic cancer, both the expression of COMP by the cancer cells and stroma were linked to a poorer overall survival of patients." (PMID 38965233, 2024). "Similar association of COMP expression with shorter OS of patients was observed when patients were stratified by the anatomical site of the primary tumor (the right and the left colon tumors)." (PMID 37207219, 2023). "Futhermore, COMP was a crucial CAFs-driven gene associated with the infiltration of M2 macrophages and acted as a promising predictive capabilities for prognosis and immunotherapy response in patients with colon cancer." (PMID 37965307, 2023). "In addition, our experimental validation demonstrated that COMP overexpression is associated with colon cancer carcinogenesis and is strongly associated with CAFs and M2 macrophage infiltration." (PMID 36671447, 2022). "For example, EGFL6 and COMP are highly associated with colon cancer." (PMID 35178071, 2021). "Therefore, we speculate that the high expression of THBS2 and COMP in colon cancer may be associated with CAFs phenotype conversion." (PMID 38827236, 2024). "Moreover, in colon cancer, increased COMP gene expression is reportedly associated with poor overall survival in a large patient cohort (n = 286), and cell line studies have shown that high COMP expression is associated with increased proliferation." (PMID 33540589, 2021). "COMP, another gene in the panel, is a prognostic factor and biomarker in colon cancer, where it promotes cell proliferation by activating the AKT pathway." (PMID 40592939, 2025). "In contrast, COMP promoted the proliferation of colon cancer and hepatocellular carcinoma cells, highlighting the diverse mechanisms by which COMP acts in different cancer types." (PMID 38615020, 2024). "In colon cancer tissues, high COMP expression correlates with a higher proportion of M0 and M2 macrophages and a lower proportion of CD8+ T cells compared to tissues with low COMP expression." (PMID 38827236, 2024). "First, we observed significant upregulation of THBS2 and COMP in colon cancer, both of which displayed significant prognostic value." (PMID 38827236, 2024). "It has been reported that COMP promotes cell proliferation during the early stages of colon cancer tumorigenesis." (PMID 36991138, 2023). "Further, COMP expression in the stroma was a predictive marker of OS for patients with primary left colon tumors." (PMID 37207219, 2023). "COMP glycoprotein has been demonstrated to be co-expressed with many EMT genes, and a clear association between high COMP expression and poor colon cancer survival has also been reported." (PMID 37838792, 2023).
colon carcinoma (continued). "In patients with primary left colon tumors, the expression of COMP by the cancer cells remained prognostic (p=0.002)." (PMID 37207219, 2023). "In colon cancer, COMP levels were found to be significantly elevated, and were strongly associated with cell adhesion and tumor progression." (PMID 36968601, 2023). "detected the expression level of COMP in colon cancer cells and found that COMP played a role in promoting the growth of colon cancer cells." (PMID 37020597, 2023). "COMP was highly expressed in colon cancer tissues, and the level of COMP decreased after colon cancer surgery." (PMID 37020597, 2023). "We also detected COMP expression levels between colon carcinoma and adjacent normal tissues and found an elevated COMP expression level in carcinoma specimens." (PMID 36671447, 2022). "We also analyzed the CMap database and proposed HDAC inhibitor, protein synthesis inhibitor, retinoid receptor agonist, and VEGFR inhibitor for targeting COMP in colon cancer." (PMID 36671447, 2022). "In summary, our study uncovered COMP as a critical CAFs-driven gene in colon cancer, which was externally and extendedly validated in multiple independent cohorts." (PMID 36671447, 2022). "COMP has been shown to be highly expressed in tumor cells and the neighboring stroma cells in breast, hepatocellular, and colon cancer." (PMID 36671447, 2022). "We also detected that COMP expression was increased in colon cancer and exhibited a stage-dependent increase, and the similar expression profile was also validated by IHC in specimens from our institution." (PMID 36671447, 2022). "Previous studies reported the survival predicting value of COMP in colorectal cancer, while, in this study, systematic analysis of various independent colon cancer cohorts revealed that high COMP expression indicated a worse outcome." (PMID 36671447, 2022). "Our findings indicated that COMP was related to M2 macrophage infiltration and acted as a convincing predictor of prognosis and immunotherapy in colon cancer patients." (PMID 36671447, 2022). "Our current study elucidates the crucial role of COMP in infiltrating M2 macrophages, predicting the prognosis and immunotherapy response of individuals with colon cancer." (PMID 36671447, 2022). "Our results showed the potential of COMP as an independent prognosis factor and biomarker for predicting immunotherapeutic response and efficacy for colon cancer patients." (PMID 36671447, 2022). "MMPs and signals of Epithelial–Mesenchymal Transition, COMP and SFRP4, were also found to be upregulated in colon cancers and associated with poor overall survival." (PMID 34824625, 2021). "Clinical evidence demonstrated that cartilage oligomeric matrix protein (COMP) has a substantial part in tumorigenesis, proliferation, and invasion of colon cancer cells." (PMID 33954114, 2021). "The method of choice was the evaluation of COMP expression by immunohistochemical staining of patients biopsies for prostate cancer and colon cancer; in the case of hepatocellular carcinoma an ELISA was used that is not IVD approved." (PMID 31737569, 2019). "Furthermore, the spatial co-localization of CAFs marker genes with THBS2, THBS4, and COMP in colon cancer supports these findings." (PMID 38827236, 2024). "Additionally, serum levels of COMP have been shown to be independent prognostic factors for breast and colon cancer." (PMID 38615020, 2024). "As a secreted protein, COMP could promote cell proliferation, prevent apoptosis, and enhance EMT in colon cancer, whereas the significance of COMP in TME and immunotherapy has rarely been studied." (PMID 36671447, 2022). "Above all, COMP was a candidate molecule for distinguishing rectal cancer from colon cancer, and regulating COMP expression may serve as a cancer-targeting strategy." (PMID 36551305, 2022).